NCR1 (natural cytotoxicity triggering receptor 1)
Description:
Cytotoxicity-activating receptor that may contribute to the increased efficiency of activated natural killer (NK) cells to mediate tumor cell lysis.
Synonyms: NK-p46; NKp46; CD335; LY94
Tractability: Antibody: UniProt places it where antibodies can reach, with high confidence; its Gene Ontology location is reachable by antibodies, with high confidence; UniProt predicts a signal peptide or a membrane-spanning region.
Gene: Protein-coding gene on chromosome 19 (54,906,148 to 54,916,140, forward strand). Ensembl gene ENSG00000189430.
Subcellular location: Cell membrane
Pathways (Reactome):
Immune System: Immunoregulatory interactions between a Lymphoid and a non-Lymphoid cell
Gene Ontology:
Molecular function: protein binding; immune receptor activity; transmembrane signaling receptor activity
Biological process: cellular defense response; immune response-inhibiting cell surface receptor signaling pathway; natural killer cell activation; regulation of natural killer cell mediated cytotoxicity; signal transduction
Cellular component: plasma membrane; SWI/SNF complex
Genetic constraint (gnomAD): Loss-of-function variants: 34 observed, 36.62 expected, observed/expected ratio (o/e) 0.93, 90% interval 0.7 to 1.24. The upper end of that interval is the gene's LOEUF score, 1.24, which puts it in group 5 of 6, group 1 being the genes least tolerant of losing a copy. Missense variants: 369 observed, 400.5 expected, observed/expected ratio (o/e) 0.92, 90% interval 0.85 to 1. Synonymous variants: 169 observed, 151.64 expected, observed/expected ratio (o/e) 1.11, 90% interval 0.98 to 1.27.
Homologues: Orthologues: chimpanzee NCR1 (97% identical), macaque NCR1 (86% identical), dog NCR1 (63% identical), pig NCR1 (62% identical), rat Ncr1 (62% identical), mouse Ncr1 (61% identical), guinea pig NCR1 (55% identical). Paralogues in human: LILRA4 (39% identical), LILRB3 (39% identical), LILRA6 (38% identical), LILRA1 (37% identical), GP6 (36% identical), LILRA2 (36% identical), LILRB5 (36% identical), LILRA5 (35% identical), LILRB1 (35% identical), LILRB2 (34% identical), FCAR (34% identical), IGSF1 (32% identical), and 13 more.
Diseases named in the same sentence as NCR1 in open-access papers:
NCR1 is named in the same sentence as 188 diseases in open-access papers, as found by Europe PMC text mining. Sharing a sentence is not in itself a finding about the gene and the disease. The quoted sentences say what the papers report.
melanoma (55 papers, 2009 to 2026). A malignant, usually aggressive tumor composed of atypical, neoplastic melanocytes. "Functionally, genetic deficiency of the NCR member NKp46, encoded by Ncr1, leads to impaired clearance of subcutaneous melanoma and T cell lymphoma, whereas transgenic overexpression enhances rejection of metastasis in mice." (PMID 39920136, 2025). "Several published literatures have clearly demonstrated that NKp46, encoded by Ncr1, is an activating receptor for NK cells, which plays critical roles in repressing the growth and metastasis of tumors, especially melanoma, via IFN-γ production." (PMID 30451838, 2018). "Ncr1 overexpression in NK cells increased NK cell immunity in two hallmark Ncr1 related pathologies, influenza virus infection and B16 melanoma." (PMID 29026144, 2017). "In a murine model for melanoma, the expression of NCR1 was crucial in order to control growth of metastases, indicating that NCR1 is involved in NK cell control of metastasis formation." (PMID 30995287, 2019). "NCR1/NKp46 is directly involved in the killing of melanoma and Lewis lung carcinoma cells and in the formation of metastases." (PMID 32038612, 2019). "The main defect of blood NK cells was a decreased expression of activating NCR1/NKp46 receptor and a positive correlation of NKp46 expression with disease outcome in stage IV melanoma patients was found." (PMID 26218530, 2015). "B16 is a mouse melanoma that expresses NCR1 and DNAM-1 ligands." (PMID 37520575, 2023). "In a Ncr1 KO murine model, there was increased metastasis caused by decreased Ncr1-regulated production of both TNFα and IFN-γ, the latter also directly decreased the ECM protein fibronectin 1 (FN1) in both melanoma and lung adenocarcinoma models." (PMID 33499238, 2021). "Our data revealed heightened expression of CD8+ T cell markers (CD8a and CD8b) and NK cell markers (NCR1 and NCR3) in melanoma patients with elevated levels of cGAS/CCL5/CXCL10." (PMID 38506049, 2024). "The findings of our study are consistent with those of another study that demonstrated that NCR1 knockout mice failed to suppress subcutaneous lymphoma and melanoma." (PMID 38891037, 2024). "In two spontaneous metastasis models, the B16F10.9 melanoma (B16) and the Lewis lung carcinoma (D122) in the NCR1 knockout mouse, NKp46/NCR1 is directly involved in the killing of B16 and D122 cells in vitro and plays an important role in controlling B16 and D122 metastasis in vivo." (PMID 25299645, 2014).
influenza (46 papers, 2010 to 2025). An acute viral infection of the respiratory tract, occurring in isolated cases, in epidemics, or in pandemics; it is caused by serologically different strains of viruses (influenzaviruses) designated A, B, and C, has a 3-day incubation period, and usually lasts for 3 to 10 days. "There is an increased incidence of human papilloma virus (HPV)- and EBV-induced cancers, and influenza infection has exhibited higher lethality in a mouse model bearing a loss of function of Ncr1, which encodes NKp46." (PMID 39066359, 2024). "This has been shown using mice deficient for Ncr1, in which the influenza infection displays increased lethality." (PMID 33375516, 2020). "Significantly, more IL2 was produced when the Ncr1 zeta and Ncr1 N139 216 238A zeta BW cells were incubated with EL4 PR8 influenza compared with the BW cells expressing the O-linked Ncr1 mutants." (PMID 27462433, 2015). "Depletion of (Asialo GM-1+) NK cells was associated with increased morbidity and mortality in the murine model, and influenza infection of NCR1 knockout mice was lethal." (PMID 33494528, 2021). "NA treatment of NCR1-Ig reduced binding to influenza (A/Puerto Rico/8/1934 (H1N1)) infected MDCK cells, although this reduction was minimal." (PMID 33494528, 2021). "We also tested the functionality of the O-glycosylated residues of Ncr1 against influenza by using the BW reporter system." (PMID 27462433, 2015). "In agreement with previous reports, following influenza infection, the binding of NKp46-Ig and NCR1-Ig was substantially increased." (PMID 22457623, 2012). "This was in accordance with a previous study, which demonstrated that NK cells from Ncr1+/gfp mice are fully functional while NK cells from Ncr1gfp/gfp mice manifest reduced activity following influenza infection and tumor development." (PMID 21887255, 2011). "In addition, we expressed the Ncr1 and O-glycosylated mutant in primary human NK cells and demonstrated that the newly identified O-glycosylated residues of Ncr1 are essential for influenza recognition." (PMID 27462433, 2015). "In mice, induced deletion of the human NKp46 homolog (NCR1) determines lethal influenza infection." (PMID 25071766, 2014). "Indeed, the murine homologue of the human NKp46 receptor (also known as Ncr1) is critical for host defense against influenza, and human NKp46 has been shown to bind viral hemagglutinins." (PMID 21829360, 2011). "Indeed Ncr1−/− (NKp46) knockout in the mouse results in lethal influenza infection." (PMID 30079068, 2018). "Others have identified genes that are protective during influenza infection, including MX1, NCR1, CCR5, IFITM3 and IL1014." (PMID 27156515, 2016). "To demonstrate that Ncr1 directly interacts with viral HA via its O-glycosylated residues, we cloned the extracellular part of the HA protein of PR8 influenza and fused it to human IgG1." (PMID 27462433, 2015). "Abnormalities in IL-15, NCR1, CD27, and an increase in T & NK cell activation traits, similar to those observed during swine flu and influenza, were prominent and may be considered a target of further investigation using a more controlled methodology." (PMID 34177897, 2021). "Collectively, these data suggest that the N-glycosylations of Ncr1 are not important for its binding to influenza and tumor cells." (PMID 27462433, 2015). "We have demonstrated that N glycosylation play little role in the recognition of mouse tumor cell lines and also showed the in-vivo importance of Ncr1 in the control of influenza virus infection by infecting C57BL/6 and BALB/c mice knockout for Ncr1 with influenza." (PMID 22615821, 2012). "Similarly, recognition of influenza virus hemagglutinin on virus-infected cells by another activating receptor, NKp46, activates lysis by human NK cells, and the murine NKp46 equivalent, NCR1, is required for protection against lethal influenza infection." (PMID 20300608, 2010).
influenza (continued). "In addition, influenza infection is lethal in mice lacking the NK cell specific receptor NKp46 (NCR1), which has been reported to be a receptor for the influenza hemagglutinin (HA) protein." (PMID 32117282, 2020). "Additionally, we demonstrate an Ncr1-mediated, dose dependent control of the PR8 influenza virus infection by infecting two inbred mouse strains, C57BL/6 and BALB/c knocked out for Ncr1 with influenza." (PMID 22615821, 2012). "Interestingly however, consistent binding of the double and triple mutated Ncr1 was observed to the coated and to the infected cells, suggesting that none of the N-glycosylated residues of Ncr1 play an essential role in its binding to influenza." (PMID 22615821, 2012). "Thus, to test whether the TM-treated Ncr1 Ig protein would still bind to influenza, we incubated EL4 cells with PR8 influenza and tested the staining with both Ncr1 proteins (TM treated or not)." (PMID 27462433, 2015).
viral infection (39 papers, 2011 to 2025). "NCR1 has been linked to a variety of diseases, including viral infections, cancer and autoimmune diseases." (PMID 39221148, 2024). "Alternatively, a recent study indicated that the CD45.1 mice have a point mutation in the Ncr1 locus that leads to an increased innate IFN-γ response to viral infection." (PMID 37938184, 2023). "Viral infections augment the expression of NCR1 (Nkp46) with an increased cytotoxic degranulation and inflammatory cytokine production." (PMID 32545516, 2020). "NKp46/Ncr1 is also a unique marker expressed on NK and on Lymphoid tissue inducer (LTI) cells and it was implicated in the control of various viral infections, cancer and diabetes." (PMID 22615821, 2012). "Finally, NCR1 is a marker of NK cell activation, but, under chronic viral infection, it was reported that NCR1-FcRγ complex dampens T-cell activity thus favoring chronic infection." (PMID 34359727, 2021). "Thus, our findings that NK cells negatively regulate virus-specific CD8 T cell responses via NCR1 in a direct manner may not only account for virus infections, but might be extended to allo-reactivity or tumor settings." (PMID 30995287, 2019). "Very recently, we discovered that FcRγ derived from natural cytotoxicity triggering receptor 1 (NCR1) curtails CD8+ T cell expansion and thereby turns an acute viral infection into a chronic one." (PMID 32093173, 2020). "NKp46 (CD335, NCR1) is a member of the natural cytotoxicity receptor (NCR) family, which is involved in the control of tumors and viral infections." (PMID 23452562, 2013). "Therefore, after investigating the role of NCR1 in acute virus infection, we examined how the absence of NCR1 influences CD8 T cell responses in chronic LCMV infection." (PMID 30995287, 2019). "However, whereas we could show that a combined loss of NKG2D, NCR1 and CD16 resulted in a significant reduction in the ability of NK cells to control viral infection and non-hematopoietic tumors, their functionality was not abrogated completely." (PMID 37520575, 2023).
acute myeloid leukemia (21 papers, 2013 to 2025). Acute myeloid leukemia (AML) is a group of neoplasms arising from precursor cells committed to the myeloid cell-line differentiation. "In line with this, phagocytes, via ROS production, efficiently downregulated NKG2D and NKp46 (natural cytotoxicity receptor 1; also known as NCR1 or CD335) surface expression in vitro, which has been proposed to mediate NK cell deficiency in patients with acute myeloid leukemia." (PMID 31535086, 2019). "Of note, a drug targeting NCR1 (SAR443579), is currently in Phase 1/2 for acute myeloid leukemia (NCT05086315)." (PMID 39482741, 2024). "In acute myeloid leukemia (AML) the down-regulation of activating receptors NKp30/NCR3 and NKp46/NCR1 correlates with defective NK-cell cytotoxicity and poor leukemia prognosis." (PMID 24391641, 2013).
colitis (19 papers, 2017 to 2025). Inflammation of the colon. "Additionally, reduced mRNA expression of Ncr1 —coding for NKp46, one of the NK triggering receptors— and a trend towards increased Lcn2 —coding for lipocalin-2, also named NGAL, a neutrophil secondary granule marker— in colons of Cd6-/- mice undergoing DSS-induced colitis was observed." (PMID 36211446, 2022).
lymphoma (16 papers, 2014 to 2025). A malignant (clonal) proliferation of B- lymphocytes or T- lymphocytes which involves the lymph nodes, bone marrow and/or extranodal sites. "In line with cell surface expression, AIDS-RL had no modification of NKp46/NCR1 specific RNA level (0.5 < normalized ratio <2 for the 6 of the 7 patients analyzed) compared with HIV + population without lymphoma." (PMID 25908934, 2014).
leukemia (14 papers, 2012 to 2025). A malignant (clonal) hematologic disorder, involving hematopoietic stem cells and characterized by the presence of primitive or atypical myeloid or lymphoid cells in the bone marrow and the blood. "Following co-culture with different tumors, primary human T-lymphocytes expressing a chimeric NCR1 molecule recognized target cells derived from lung, cervical carcinoma, leukemia and pancreatic cancer." (PMID 25431955, 2014). "We and others showed that NCR1 is central to the recognition and lysis by NK cells of viral-infected and tumor cells such as carcinomas, neuroblastomas, and leukemias." (PMID 25431955, 2014). "This association protected NK from the downregulation of activating-receptor expression (more particularly NKp46/NCR1) induced by leukemia cells; thus, it enhanced NK cytotoxicity and tumor immune control with significant improvement in leukemia-free survival." (PMID 22899948, 2012).
diabetes (13 papers, 2012 to 2025). "To directly demonstrate that blocking of NKp46 in NOD mice will block diabetes development, we injected NCR1.15 into NOD mice every other day (100μg per injection) beginning in week eight." (PMID 25719382, 2015). "Moreover, immunization of NOD mice using NKp46-Ig and NCR1-Ig fusion proteins significantly reduced diabetes incidence, without depleting the NK cell population." (PMID 24478773, 2014). "NKp46 involvement in T1D was not specific to NOD mice: when diabetes was induced in WT and Ncr1gfp/gfp KO mice using a LDST protocol, diabetes development was significantly impaired in mice lacking NCR1." (PMID 24478773, 2014).
liver fibrosis (13 papers, 2014 to 2025). "Mechanistically, NKp46/NCR1, a specific marker of NK cells, mediates the killing of human and mouse HSCs through unknown ligands, thus resulting in the attenuation of liver fibrosis." (PMID 40494889, 2025). "Natural cytotoxicity triggering receptor 1 (NKp46)+ NK cells can inhibit the progression of NASH and liver fibrosis via suppressing the expression of profibrogenic genes as well as M2 polarization (anti-inflammatory phenotype) of liver macrophages." (PMID 34944709, 2021).
lung carcinoma (12 papers, 2013 to 2025). "Human NK cells express both NCR1 and NCR3 at high levels, and low expression of NCR3 specifically has been associated with poor prognosis in lung cancer." (PMID 40443661, 2025). "In line with our mouse data, CB1 and CB2 expression were not only seen in lung cancer cells, but also in infiltrated immune cells, such as CD3+ T and CD8+ T cells, NKp46/NCR1+or CD56+ NK cells, and CD163+ macrophages." (PMID 36700219, 2022). "In that study, infiltration of macrophages and CD56dim-NK-cells was increased in lung cancer BM, similar to the increased CD163-positive M2 to iNOS-positive M1 macrophage and NCR1-positive NK cell to CD3-positive T-cell ratios." (PMID 34638378, 2021).
Obesity (11 papers, 2019 to 2023). Accumulation of substantial excess body fat. "This seeming paradoxical state may be caused by their unique local microenvironments, as obesity increases the expression of the ligands of NK cell activating receptor NCR1 on adipocytes, thereby stimulating the IFN-γ production and local expansion of NK cells." (PMID 32983138, 2020). "NK cells are directly activated in cases of obesity through the upregulation of NK cell-activating receptors on adipocytes; more specifically through the expression of NKp46, known as natural cytotoxicity triggering receptor 1 (NCR1) in mice." (PMID 34489979, 2021). "Obesity was also shown to trigger the expression of NK cell ligand-NCR1 on adipocytes and to lead to higher frequencies of NK cells and increased IFN-γ production by those NK cells within the adipose tissue." (PMID 31736971, 2019). "During obesity, adipocytes increase their expression of NK cell activating receptor (NCR1) which may be responsible for the expansion of local VAT NK cells and their IFNγ production." (PMID 32499756, 2020).
COVID-19 (10 papers, 2020 to 2023). A disease caused by infection with severe acute respiratory syndrome coronavirus 2. "In support of histological evidence of lung epithelium damage, concentrations of cell death–related proteins tumor necrosis factor–α (TNFα), caspase 8, TRAIL, EDAR, and NCR1 were altered in plasma from patients with COVID-19 relative to normal controls." (PMID 34648357, 2021). "Comparison between the disease conditions indicated significantly stronger expression of certain NK cell receptors (CD160, KLRC2, KLRC3, KLRF1, KIR3DL2, NCR1, NCR3) along the SLEC lineage in mild COVID-19 compared to severe COVID-19." (PMID 36591270, 2022).
type 1 diabetes (10 papers, 2013 to 2024). "We recently reported that the murine activating receptor NKp46 (NCR1) is essential for the development of type 1 diabetes (T1D), an autoimmune disease prevalent throughout the Western world." (PMID 25719382, 2015).
breast cancer (7 papers, 2011 to 2023). A primary or metastatic malignant neoplasm involving the breast. "We analysed the expression of the NCRs, NCR1, NCR2, and NCR3 in NK cells from breast cancer patients and healthy donors using flow cytometry." (PMID 28145491, 2017). "The breast cancer cell lines BT-20 and SKBR3, the human prostate adenocarcinoma cell line LNCaP and the human colon cancer cell line HCT116 lack expression of CD3 (T cell marker) and CD56 (NK cell marker) and show very low expression of CD335 (NK cell marker), also known as NKp46/NCR1." (PMID 37593736, 2023).
colorectal cancer (7 papers, 2013 to 2026). A primary or metastatic malignant neoplasm that affects the colon or rectum. "Combinations of CD3-, CD56+, CD8+ and NCR1+ IHC staining have previously been used for the identification of NK cells in lymph nodes, colorectal cancer tissue and in the gut mucosa of HIV infected individuals." (PMID 27219121, 2016).
prostate carcinoma (6 papers, 2008 to 2022). A carcinoma that arises from epithelial cells of the prostate gland. "Another study showed that hypoxia upregulates HIF-1, and suppresses the NCR1/NKp46 pathway by upregulating miR-224, which affects the killing capability of NK cells in prostate cancer; thus, inducing immune escape of tumor cells." (PMID 35538543, 2022). "Hypoxia is a typical feature of prostate cancer, and a relationship between HIF1A-induced microRNA 224 (miR224) and natural cytotoxicity triggering receptor 1 (NCR1) has been uncovered in hypoxic prostate tumors." (PMID 35659268, 2022).